TFAM (transcription factor A, mitochondrial)
Description:
Binds to the mitochondrial light strand promoter and functions in mitochondrial transcription regulation. Component of the mitochondrial transcription initiation complex, composed at least of TFB2M, TFAM and POLRMT that is required for basal transcription of mitochondrial DNA. In this complex, TFAM recruits POLRMT to a specific promoter whereas TFB2M induces structural changes in POLRMT to enable promoter opening and trapping of the DNA non-template strand. Required for accurate and efficient promoter recognition by the mitochondrial RNA polymerase. Promotes transcription initiation from the HSP1 and the light strand promoter by binding immediately upstream of transcriptional start sites. Is able to unwind DNA. Bends the mitochondrial light strand promoter DNA into a U-turn shape via its HMG boxes. Required for maintenance of normal levels of mitochondrial DNA. May play a role in organizing and compacting mitochondrial DNA.
Synonyms: mtTFA; MtTF1; TCF6; TCF6L2; MTDPS15; TCF6L1; TCF6L3
Tractability: Small molecule: a structure with a bound ligand is known. PROTAC: ubiquitination databases record sites on it; its protein half-life has been measured.
Target class: Transcription factor
Gene: Protein-coding gene on chromosome 10 (58,385,345 to 58,399,220, forward strand). Ensembl gene ENSG00000108064.
Subcellular location: Mitochondrion; Mitochondrion matrix, mitochondrion nucleoid
Subcellular location (Human Protein Atlas): Mitochondria
Pathways (Reactome):
Gene expression (Transcription): Mitochondrial transcription initiation
Metabolism of proteins: Mitochondrial protein degradation
Organelle biogenesis and maintenance: Transcriptional activation of mitochondrial biogenesis
Gene Ontology:
Molecular function: chromatin binding; mitochondrial promoter sequence-specific DNA binding; mitochondrial transcription factor activity; protein binding; RNA binding; sequence-specific DNA binding; heat shock protein binding; transcription coactivator binding
Biological process: mitochondrial transcription; transcription initiation at mitochondrial promoter; response to hypoxia; response to nutrient
Cellular component: mitochondrial matrix; mitochondrial nucleoid; mitochondrion; nucleus; protein-containing complex; cytosol
Genetic constraint (gnomAD): Loss-of-function variants: 12 observed, 26.18 expected, observed/expected ratio (o/e) 0.46, 90% interval 0.29 to 0.74. The upper end of that interval is the gene's LOEUF score, 0.74, which puts it in group 3 of 6, group 1 being the genes least tolerant of losing a copy. Missense variants: 225 observed, 279.3 expected, observed/expected ratio (o/e) 0.81, 90% interval 0.72 to 0.9. Synonymous variants: 105 observed, 90.08 expected, observed/expected ratio (o/e) 1.17, 90% interval 0.99 to 1.37.
Homologues: Orthologues: macaque TFAM (87% identical), chimpanzee TFAM (83% identical), pig TFAM (72% identical), dog TFAM (72% identical), rat Tfam (62% identical), mouse Tfam (61% identical), rabbit TFAM (61% identical), guinea pig TFAM (56% identical), zebrafish tfam (39% identical), Caenorhabditis elegans hmg-3 (13% identical), Caenorhabditis elegans hmg-4 (12% identical). Paralogues in human: TOX2 (18% identical), HMGB1 (17% identical), HMGB2 (17% identical), HMGB3 (17% identical), HMGB1P1 (17% identical), UBTF (17% identical), SP100 (16% identical), SSRP1 (16% identical), TOX3 (16% identical), TOX (15% identical), TOX4 (15% identical), SMARCE1 (14% identical), and 8 more.
Diseases named in the same sentence as TFAM in open-access papers:
TFAM is named in the same sentence as 226 diseases in open-access papers, as found by Europe PMC text mining. Sharing a sentence is not in itself a finding about the gene and the disease. The quoted sentences say what the papers report.
breast carcinoma (38 papers, 2015 to 2025). "Previous studies showed some mutations in the gene coding for DNA polymerase gamma or TFAM in breast cancers or colon cancers with low mtDNA copy numbers." (PMID 27231905, 2016). "Additionally, TFAM SNPs were reported to be associated with prostate, colorectal, breast, uterine, ovary, and cervical cancer and TFAM expression alterations in lung and breast cancer." (PMID 36833361, 2023). "In summary, this study suggests that the herbal recipe SLC has the potential to act as an agent for inhibiting OXPHOS through the PDK1/PDHA1 and SIRT1/PGC-1α/NRF1/TFAM signaling axis to treat HER2-positive breast cancer." (PMID 41465397, 2025). "TFAM is involved in tumor metastasis in breast cancer, and its protein levels are elevated in high-grade serous ovarian cancer tumor biopsies (according to the reference value)." (PMID 39927160, 2025). "TFAM regulates mitochondrial DNA transcription and replication, and its expression and function has been shown to be of importance for metastasis in breast cancer." (PMID 41149583, 2025). "Knockdown of TFAM expression in breast cancer reduces the mtDNA copy numbers and activates Calcineurin-mediated mitochondrial retrograde signaling, upregulates mesenchymal gene expression to induce EMT, and generates cancer stem cells." (PMID 38589371, 2024). "TFAM is upregulated in prostate cancer, glioma, and breast cancer, and showing a positive correlation with poor patient prognosis." (PMID 38589371, 2024). "We demonstrated that ZNF468 up-regulation of TFAM not only contributed to the growth and migration of breast cancer cells but also reduced the sensitivity of the cells to cisplatin treatment." (PMID 38429817, 2024). "In breast cancer, TFAM-positive patients have been reported to have a relatively poor clinical prognosis." (PMID 37627097, 2023). "TP73-AS1 mediates the proliferation of breast cancer cells by inhibiting miR-200a to regulate the expression of TFAM." (PMID 35432537, 2022). "The co-inhibition of iNOS and AKT reduced mitochondrial density and TFAM in additional lung and breast cancer cell lines, suggesting that other cancer cells also rely on the regulation of mitochondrial biogenesis by iNOS and pAKT downstream of EPOR." (PMID 36052260, 2022). "In agreement with our findings in HCC, increased expression of another mitochondrial transcription factor TFAM has also been observed in various human cancers, including breast cancer, bladder cancer, colon cancer, glioma, and non-small cell lung cancer." (PMID 33771980, 2021). "Studies of breast cancer cells demonstrated that miR-200a represses the expression of TFAM (mitochondrial transcription factor A), the principal transcription factor of mitochondria, an effect that hampers the proliferative capacity of cells." (PMID 34884985, 2021). "Increased TFAM expression has also been shown to predict poor clinical outcome in several types of malignancies, including ovarian cancer, breast cancer, and endometrial carcinoma." (PMID 33771980, 2021). "One of the targets of this microRNA is mitochondrial transcription factor A (TFAM) whose significance has been described in various malignancies including breast cancer." (PMID 32872155, 2020). "Fan found that MiR-199a-3p enhanced breast cancer cell sensitivity to cisplatin by downregulating TFAM." (PMID 30862036, 2019). "Estrogen treatment increases mitochondrial mass, the DNA-binding activity of NRF1, a regulator of TFAM, and the level of TFAM, and TFAM shRNA inhibits colony formation in E2-treated breast cancer cells." (PMID 30486409, 2018). "TP73-AS1 has been demonstrated to promote breast cancer proliferation through miR-200a-mediated TFAM inhibition." (PMID 29614984, 2018). "The expression level of TFAM increases during the induction of EMT in breast cancer cells." (PMID 39927160, 2025). "In turn, inhibition of TFAM expression could attenuate cisplatin resistance in breast cancer cells and induce apoptotic and proliferative effects." (PMID 38132441, 2023).
breast carcinoma (continued). "Yao determined that microRNA-200a inhibits cell proliferation by targeting TFAM in breast cancer." (PMID 30862036, 2019). "Further, in human breast cancer SUM159 cells, D9 activates ClpP, promoting the degradation of mitochondrial transcription factor A (TFAM) and mitochondrial Tu translation elongation factor (TuFM)." (PMID 40395852, 2025). "Overall, SLC influences oxidative phosphorylation via the PDK1/PDHA1 and SIRT1/PGC-1α/NRF1/TFAM signaling pathways and downregulates the HER2 pathway, thereby ultimately inhibiting HER2-positive breast cancer progression." (PMID 41465397, 2025). "We found that VEGFR2 blockade inhibited cancer cell proliferation of the two breast cancer cell lines, MCF-7 and MDA-MB-231, and that the inhibition was achieved by enhancing mitochondrial transcription factor A (TFAM) expression and mitochondrial biogenesis." (PMID 33628590, 2021). "Therefore, new therapeutic targets have been investigated, and TFAM is a strong candidate target since its expression is altered in several types of cancer, including glioma, colorectal cancer, epithelial ovarian carcinoma, bladder cancer, breast cancer, lung cancer, and colon cancer." (PMID 29747444, 2018). "Among them, TR57 inhibits the growth and proliferation of SUM159 tumor cells of breast cancer by inducing ISR and endoplasmic reticulum stress response marker ATF4 and CHOP protein expression levels, inhibiting TFAM and TuFM protein expression levels, and inhibiting colony formation ability." (PMID 40395852, 2025). "In addition, TP73-AS1 boosted cell proliferation, invasion, and migration, and functioned as a ceRNA with miR-200a to prevent binding of TFAM, dampening the TP73-AS1/miR-200a/ZEB1 and TP73-AS1/miRNA-125a-3p/ metadherin axis in breast cancer." (PMID 35614413, 2022).
Sepsis (28 papers, 2010 to 2025). Sepsis is defined as life-threatening organ dysfunction caused by a dysregulated host response to infection. "Adequate compensation of mitochondrial damage seems to play an important role in determining the outcome of sepsis, as mRNA expression of Peroxisome Proliferator-activated Receptor Gamma Coactivator 1-alpha (PGC1α) (marker of biogenesis upstream of TFAM) is associated with survival from sepsis." (PMID 33494815, 2021). "This may indicate a potential association between intramitochondrial TFAM abundance and severity of the sepsis-related organ dysfunction." (PMID 33273525, 2020). "In bacterial sepsis, a reduced number of protein interactions between TFAM and TFB2M measured in PBMCs was associated with inefficient mitochondrial recovery and increased mortality in sepsis." (PMID 40458415, 2025). "For instance, melatonin can mitigate sepsis-induced acute kidney injury by promoting mitochondrial autophagy through SIRT3-mediated deacetylation of mitochondrial transcription factor A (TFAM)." (PMID 39544947, 2024). "Recently, it has been shown that mitochondrial transcription factor A (TFAM), which is key in mitochondrial biogenesis, is significantly decreased in sepsis." (PMID 37107158, 2023). "We also showed that BAM15 increased TFAM expression, which is downstream of PGC1α, in kidney during an early phase of sepsis." (PMID 36757801, 2023). "Consistent with other studies on sepsis, we found an upregulation of TFAM mRNA in symptomatic COVID-19 cases compared to asymptomatic and healthy controls." (PMID 37869674, 2023). "TFAM stimulation can improve redox and mitochondrial activity, motor function, and high survival rates in a sepsis model." (PMID 36333747, 2022). "Expression of the biogenesis marker TFAM was lower in sepsis-AKI patients than in control subjects (p < 0.01)." (PMID 33494815, 2021). "Sepsis-AKI patients had lower mRNA expression of TFAM (marker for biogenesis) and PINK and PARKIN (markers for mitophagy), but no change in mRNA expression of MFN2 and DRP1 (markers for fusion and fission)." (PMID 33494815, 2021). "To assess the functional relevance of intramitochondrial TFAM in PBMCs from sepsis patients, we quantified the interactions of TFAM and mitochondrial Transcription Factor 2B, also known as the mitochondrial core transcription initiation complex." (PMID 33273525, 2020). "In this context, our results shed light on a potential intracellular maldistribution of TFAM in sepsis and endotoxemia resulting in decreased intramitochondrial TFAM, although its source, i.e., extramitochondrial TFAM, is conserved or even increased." (PMID 33273525, 2020). "In this context, we also found a 1.8-fold greater extramitochondrial TFAM protein expression in sepsis patients compared to healthy controls (p = 0.001)." (PMID 33273525, 2020). "Our study reveals that TFAM abundance in mitochondria decreases during the early inflammatory phase of sepsis, despite cellular upregulation of TFAM expression." (PMID 33273525, 2020). "Extramitochondrial TFAM protein expression in sepsis patients was 1.8-fold greater compared to controls (p = 0.001), whereas intramitochondrial TFAM abundance was approximate 80% less (p < 0.001)." (PMID 33273525, 2020). "This protein maldistribution of TFAM could explain the observed diverge between TFAM mRNA expression and TFAM protein activity in sepsis and now in this study in patients with COVID-19 and also likely include other nuclear-encoded mitochondrial proteins." (PMID 40458415, 2025). "This is consistent with our findings that the expression levels of mitochondrial biosynthetic proteins such as PGC‐1α, NRF2, and TFAM were significantly elevated in mice with sepsis, and the expression of biosynthetic proteins was higher after 67% H2 treatment." (PMID 39258790, 2024).
Sepsis (continued). "Since this paradox may relate to an altered intracellular distribution of TFAM in sepsis, we tested the hypothesis that enhanced extramitochondrial TFAM expression does not translate into increased intramitochondrial TFAM abundance." (PMID 33273525, 2020). "Recent studies, however, provide growing evidence that activation of mitochondrial biogenesis in sepsis, although associated with an increased intracellular TFAM expression, is not necessarily accompanied by recovery of mitochondrial function." (PMID 33273525, 2020). "The ability to resolve a critical condition such as sepsis-induced organ failure hence could depend on the ability to increase intramitochondrial TFAM abundance so as to restore adequate mitochondrial function." (PMID 33273525, 2020). "Taken together this suggests that intracellular TFAM maldistribution could be an important feature in sepsis." (PMID 33273525, 2020). "Notably, the early inflammatory response in sepsis amplifies expression and activation of factors stimulating mitochondrial biogenesis and repair such as TFAM, in line with our findings." (PMID 33273525, 2020). "Indeed, it seems evolutionarily prudent that an inflammatory response, especially to sepsis, triggers TFAM expression to mitigate harm inflicted by excessive inflammation." (PMID 33273525, 2020). "Thus, decreased renal mtROS by BAM15 may promote TFAM expression in the septic kidney and inhibit sepsis-AKI progression." (PMID 36757801, 2023). "Aside from mechanistic considerations, it is intriguing to speculate that the extent and duration of the apparent intracellular TFAM maldistribution might represent a prognostic biomarker, since TFAM/TFB2M protein interactions strongly correlated with the SOFA score of our sepsis patients." (PMID 33273525, 2020). "In an in vitro model of sepsis-induced hepatocyte injury, melatonin treatment increased the protein levels of PGC-1α, NRF1, and TFAM, as well as reduced MDA levels and increased SOD activity." (PMID 40429795, 2025). "Studies have shown that LPS-induced sepsis results in upregulation of NRF1 and TFAM, which in turn stimulates mtDNA replication and mitochondrial biogenesis." (PMID 37101253, 2023). "Their study revealed that mitochondrial biogenesis markers, including PGC-1α, NRF1, and TFAM, and mitochondrial fusion were decreased by TRPA1 blocker treatment in kidney tissues from either healthy or sepsis mouse." (PMID 37287081, 2023). "Altogether, administration of exogenous NaHS provided protective effect against myocardial mitochondrial damage in sepsis through upregulation of PGC-1α and Nrf2 expression levels and promotion of mitochondrial biogenesis by transcription of TFAM." (PMID 35706715, 2022). "Despite increased extramitochondrial TFAM both intramitochondrial TFAM abundance and the functionally important protein interaction with TFB2M are decreased in PBMCs from sepsis patients." (PMID 33273525, 2020). "During LPS-induced sepsis, the nuclear respiratory factor-1 (NRF-1), which is a transcriptional activator of mitochondrial transcription factor A (TFAM), is upregulated in hepatocytes." (PMID 31671729, 2019). "We found that sepsis stimulates staggering increases in both RAGE expression and its physical interaction with TFAM, and that both responses are mtROS-dependent." (PMID 26448624, 2015). "If the authors are correct, then impaired “mitolocalization” of TFAM and TF2BM may represent a novel component of MQC during sepsis that is worthy of further study." (PMID 39301036, 2024). "Thus, the mitochondrial biogenesis mediators PGC-1α, mitochondrial transcription factor A (TFAM), and nuclear respiratory factor 1 (NRF-1) are upregulated in the second phase of sepsis." (PMID 33919780, 2021). "Thus, an elevated cytosolic mRNA and protein concentration of TFAM, not necessarily transposes in effective mitochondrial biogenesis during severe bacterial and viral infections, especially in sepsis." (PMID 40458415, 2025).
Sepsis (continued). "Overall, the authors’ study raises important questions of whether transcriptional activation alone is enough to induce mitochondrial biogenesis, or whether defective localization of transcription factors (eg, TFAM, TF2BM) represents an additional lesion in MQC during sepsis." (PMID 39301036, 2024). "The compensatory upregulation of genes and proteins regulating oxidative homeostasis, such as PGC1α, TFAM and SOD2, are seen in sepsis survivors in response to increased oxidative stress and ROS production, and might be a possible explanation for resilience and recovery in critical illness." (PMID 36982590, 2023). "This study proved that the levels of SIRT1, PGC-1α, UCP2, TFAM, and COXIV all decreased in septic mice, the effect of which was reconciled by nanoFe treatment (vs. the CLP group, B P < 0.05), indicating the positive role of nanoFe in improving mitochondrial biogenesis during sepsis." (PMID 36064371, 2022). "In conclusion, our findings, which demonstrate a diminished mitochondrial TFAM abundance in sepsis and endotoxemia, may help to explain the paradox of lacking bioenergetic recovery despite enhanced TFAM expression." (PMID 33273525, 2020). "Similar to PGC1α, a marked decrease in TFAM protein levels has been observed in sepsis-induced diaphragm damage, which might be the result of a failure of translocation of precursor TFAM into mitochondria for final initialization rather than nuclear gene suppression." (PMID 36982590, 2023). "Supporting the hypothesized role of TLR9 pathway in sepsis, our results showed an increase in myocardial expression of MYD88 and RAGE, both of which function as downstream TLR9 factors, as well as a formation of physical interaction between RAGE and its ligand TFAM." (PMID 26448624, 2015).